S100A9 (S100 calcium binding protein A9)
Diseases named in the same sentence as S100A9 in open-access papers (continued):
Sharing a sentence is not in itself a finding about the gene and the disease.
diabetes (continued). "S100 calcium-binding protein A9 was found to be significantly increased in diabetes mellitus." (PMID 41155408, 2025). "However, we previously validated the metabolic effects of S100A9 in a streptozotocin-induced diabetes mouse model, ruling out the potential involvement of DT-induced neuronal loss." (PMID 40874857, 2025). "S100A9 and S100A8 are associated with the prognosis of diabetes mellitus and obesity." (PMID 36837510, 2023). "Our data indicate that S100A9 acts in an extracellular manner; hence means aimed at increasing plasmatic S100A9 content could be of therapeutic value in context of diabetes." (PMID 35840613, 2022). "In addition, S100A9, which is constitutively expressed in neutrophils and monocytes, was significantly increased in obese diabetes patients, and the increased levels of S100A9 were related to the macrophage content in obesity." (PMID 35412419, 2022). "Coupled with the only marginal increase in plasmatic S100A9 in decompensated patients with diabetes, our data are in favor of the development of an S100A9-based adjunctive therapeutic approach aimed at achieving better metabolic control in patients with diabetes suffering from ID." (PMID 35840613, 2022). "Diabetic nephropathy (DN), a severe complication of diabetes and a leading cause of end-stage renal disease, is strongly associated with chronic inflammation triggered by damage-associated molecular patterns (DAMPs), such as high-mobility group box 1 (HMGB1), S100A8, and S100A9." (PMID 41367913, 2025). "Therefore, as we demonstrated that increasing the circulating level of S100A9 is able to improve the metabolic imbalance caused by ID, our murine and human data provide scope for further increasing plasmatic S100A9 as a potential therapeutic clinical avenue in diabetes." (PMID 35840613, 2022). "These variables included sex, age, comorbidity with diabetes or hypertension, APACHE II score, S100A9, PCT, lactate, and CRP." (PMID 40478888, 2025). "With regard to diabetes and the eye, systemic levels of the S100A8 and S100A9 protein strongly correlated with the severity of diabetic retinopathy in patients with type 2 diabetes." (PMID 38153746, 2023). "The cumulative research supports our findings and it becomes pertinent to propose S100A9/S100A8 a potent biomarker for tuberculosis and diabetes copathogenesis." (PMID 33156824, 2020).
hepatocellular carcinoma (34 papers, 2014 to 2025). A malignant tumor that arises from hepatocytes. "Meanwhile, S100A9 is also one of the diagnostic or prognostic candidate biomarkers for a variety of diseases, for example, gastric, bladder and hepatocellular carcinoma." (PMID 36010914, 2022). "Furthermore, the cellular expression of DEGs from eosinophils such as IFITM1 and S100A9 was associated with the progression of inflammatory‐mediated disease‐driven hepatocellular carcinoma via upregulated mitochondrial oxidative phosphorylation genes (MT‐ND1 and MT‐ND2)." (PMID 41190282, 2025). "S100A8/S100A9 co-expression in hepatocellular carcinoma cells promotes malignant progression by induction of ROS, down-regulation of p38 MAPK signaling, cell survival, and resistance to tumor necrosis factor (TNF)-α-induced apoptosis." (PMID 36609243, 2023). "Reported mechanisms include that S100A9 enhances cancer stem-like properties of hepatocellular carcinoma." (PMID 37171396, 2023). "Studies have showed that S100A9 treatment enhanced the survival and invasiveness of three hepatoma cell lines, HepG2, SMMC-7721, and Huh7, and S100A9 also facilitated tumor development in vivo in a xenograft mouse model." (PMID 35992798, 2022). "S100A9 is a member of the S100 family of calcium-binding proteins and is overexpressed in many human tumors in addition to hepatocellular carcinoma (HCC)." (PMID 35992798, 2022). "For example, high CBX6 expression promotes cell growth by regulating the S100A9/NF-κB/MAPK pathway in hepatocellular carcinoma." (PMID 34395271, 2021). "Elevated serum S100A9 indicated poor prognosis in hepatocellular carcinoma after curative resection." (PMID 31467879, 2019). "Second, we examined the effects of vildagliptin and M20.7 on mRNA expression levels of inflammation-associated genes, such as S100A8, S100A9, and TNF-α, in human hepatoma HepG2 and monocytic HL-60 cells." (PMID 27759084, 2016). "It is reported that S100A9 promotes cell growth and invasion in hepatocellular carcinoma through stimulating MAPK signaling cascades." (PMID 27588397, 2016). "We further examined the effects of vildagliptin and its major metabolite M20.7 on the mRNA expression levels of S100A8 and S100A9 in human hepatoma HepG2 and leukemia HL-60 cells." (PMID 27759084, 2016). "DCLK1 silencing inhibits S100A9 expression and hepatoma cell migration." (PMID 25948779, 2015). "Furthermore, in hepatocellular carcinoma, S100A9 accelerates tumor progression by recruiting ubiquitin specific peptidase 10 (USP10) and Phosphoglycerate Mutase Family Member 5 (PGMFM5) to form a trimer that facilitates mitochondrial fission and ROS production." (PMID 40630623, 2025). "Thus, targeting S100A9 may be a promising therapeutic strategy for patients with hepatocellular carcinoma." (PMID 37171396, 2023). "For example, Chiou and colleagues successfully used these data to identify S100A9 and GRN as combinatorial biomarkers for early identification of hepatocellular carcinoma (HCC) from urine." (PMID 37168844, 2023). "Downregulation of DCLK1 inhibits HCV replication, hepatoma cell migration, tumor growth in an HCC xenograft model, EMT, and expression of myeloid-derived S100A9 protein, which suppresses anti-tumor immunity." (PMID 32601309, 2020). "S100A9 interacts with RAGE and promotes cell growth of human hepatocellular carcinoma cells by activating ERK1/2 and p38 MAPK signaling pathways." (PMID 32149126, 2020). "However, the expression, distribution, and clinical significance of S100A9 in hepatocellular carcinoma (HCC) remain unclear." (PMID 34157683, 2021). "Recently, S100A9 has been reported to be regulated by some pathogen infection and exerted a promoting role in several types of cancer such as Hepatitis B virus (HBV)-related hepatocellular carcinoma (HCC) and HPV-infected skin lesions and cancer." (PMID 34093546, 2021).
hepatocellular carcinoma (continued). "For the S100A8 partnering protein S100A9, it was suggested that it is expressed by CCR2+ TAMs in hepatocellular carcinoma (HCC), where CCR2+ TAMs presented the same expression pattern as S100A9+ TAMs and were co-localized with CD31+ endothelial cells in areas of dense vascularisation." (PMID 34209679, 2021).
asthma (33 papers, 2010 to 2025). "S100A8 and S100A9 are alarmins implicated in various chronic inflammatory conditions, including asthma." (PMID 35837410, 2022). "Hae-Sim Park and colleagues at Ajou University in Suwon, South Korea, investigated the mechanism by which S100A9 activates neutrophils to induce the airway inflammation and other changes associated with asthma." (PMID 34285336, 2021). "Earlier studies found that S100A9 is elevated in several diseases, such as neutrophilic inflammation in asthma, insulin deficiency, atopic dermatitis and Parkinson’s disease." (PMID 33827454, 2021). "The protein profile in patients with controlled (CA) and uncontrolled asthma (UA) revealed an increase in human neutrophil peptide-2, S100A9, β-amylase, neutrophil gelatinase-associated lipocalin, 4-aminobutyrate transaminase, and cystatin SA in patients with UA." (PMID 35628512, 2022). "The increased expression of S100A8 was demonstrated in peripheral blood mononuclear cells at the time of asthma exacerbation, while additional S100A9 was elevated in neutrophils and macrophages in patients with untreated asthma." (PMID 40723867, 2025). "Paquinimod, a quinoline-3-carboxamid inhibiting S100A9, decreases the number of inflammatory cells in animal models; thus, it should be investigated further in efforts to find a novel asthma treatment." (PMID 40723867, 2025). "A clinical study demonstrated that S100A9 levels were higher in sputum from patients with severe asthma and neutrophil-dominant inflammation compared to sputum from eosinophil-dominant groups." (PMID 40861440, 2025). "Until now, S100A4, S100A8/S100A9 (calprotectin), S100A11, and S100A12 have been implicated in the pathophysiology of asthma, exhibiting both similarities and differences in their mechanisms of action." (PMID 41164170, 2025). "S100A8 and S100A9 can promote mucus hypersecretion typical of asthma in BECs, which is consistent with our previously published works documenting reduced MUC5AC post-BT along with IL-13+ cells in bronchial biopsies collected from a similar cohort." (PMID 37996952, 2023). "We first documented baseline expression of S100A7, S100A8 and S100A9 genes in severe asthma and compared to BECs obtained from healthy controls." (PMID 37996952, 2023). "Lee and colleagues found that S100A9 levels were higher in sputum from patients with severe uncontrolled asthma with neutrophilic inflammation than in sputum from eosinophilic and paucigranulocytic groups." (PMID 37996952, 2023). "Peripheral blood neutrophils in patients with asthma induce airway epithelial cells to produce S100A9 and further induce M1 macrophages to polarize through extracellular signal-regulated kinase pathway, which aggravates asthma." (PMID 35619697, 2022). "Transcripts of S100A9 are upregulated in peripheral blood mononuclear cells during asthma exacerbation." (PMID 33791048, 2021). "We previously reported the relationship of S100A9 to the development of neutrophil-dominant inflammation in the CFA/OVA-induced murine model of asthma." (PMID 33791048, 2021). "The function of S100A9 was evaluated using airway epithelial cells (AECs) and PBNs/M0 macrophages from asthmatic patients, as well as a mouse asthma model." (PMID 34285336, 2021). "Recently, we showed that S100A9 initiates and amplifies neutrophilic inflammation in asthmatics and in animal models of asthma." (PMID 33791048, 2021). "The role of S100A9 in NA was confirmed in vivo using 3 types of murine asthma models (NA, EA, and MA)." (PMID 34285336, 2021). "S100A9 enhances the migration of fibrocytes in asthma exacerbations as well as chronic obstructive asthma." (PMID 34239729, 2021). "We believe that the inflammatory response due to S100A8 and S100A9 is a critical factor in asthma pathogenesis." (PMID 32174780, 2020). "S100A8 gene expression is increased in blood samples obtained from children with asthma, and S100A9 is increased in the sputum of patients with asthma and COPD." (PMID 32973796, 2020).
asthma (continued). "Elevated S100A9 level in sputum is a potential biomarker of neutrophilic inflammation in severe asthma." (PMID 32680574, 2020). "Overexpression of MUC5A in horses with severe asthma suggests a possible link of S100A9 with mucus hyperproduction." (PMID 28886691, 2017). "S100A9 expression level appears to play a role in asthma, but a definitive study on the intracellular regulatory effects of S100A9 on ASMCs proliferation is lacking." (PMID 28050155, 2016). "Our previous study showed that S100A9 is one of the differentially expressed genes in a rat lung model of asthma." (PMID 28050155, 2016). "S100A8 and S100A9 are important pathogenic mediators in severe asthma because airway resident cells express TLR4, which binds to S100A8 and S100A9, and because both proteins induce pro-inflammatory responses." (PMID 25973752, 2015). "However, S100A9 levels in sputum are seen higher in neutrophilic uncontrolled asthma patients compared to controlled asthma cases." (PMID 41164170, 2025). "Furthermore, S100A9 levels showed a significant correlation with the percentage of neutrophils in the sputum of asthma patients." (PMID 40861440, 2025). "This protein is released by activated neutrophils; S100A9 levels were elevated in samples from patients suffering from neutrophilic asthma than in the ones from healthy individuals, thus presenting a potential for this protein as a biomarker for asthma." (PMID 40723867, 2025). "Elevated S100A9 levels in severe asthma suggest involvement in disease progression." (PMID 38062491, 2023). "Similarly, S100A9 is elevated in the sputum of neutrophilic inflammation in severe uncontrolled asthma." (PMID 33791048, 2021). "Significantly increased numbers of total cells, neutrophil counts, and S100A9 levels in BALF were noted in the NA and MA groups compared to the EA group, and the highest neutrophil counts and S100A9 levels were noted in the NA group compared to the other 2 asthma groups (P < 0.001 for all)." (PMID 34285336, 2021). "In addition, PBNs obtained from patients with severe asthma were found to induce increased production of IL-1β, IL-6, and IL-8 in response to LPS plus S100A9, which further activated macrophages and AECs." (PMID 34285336, 2021). "A calcium-binding protein called S100A9 could be used as a biomarker for diagnosing a phenotype of asthma called neutrophilic asthma, and might also be a suitable target for drugs to treat the condition." (PMID 34285336, 2021). "S100A9 levels are significantly higher in uncontrolled neutrophilic asthma compared to uncontrolled eosinophilic asthma, chronic obstructive pulmonary disease, and controlled asthma." (PMID 29359169, 2017). "Further research is required to understand the function of S100A9 in severe asthma." (PMID 29359169, 2017). "Proteomics study showed that S100A9 in sputum could be a potential biomarker of neutrophilic inflammation in severe uncontrolled asthma." (PMID 28050155, 2016). "Our study aimed to determine the effect of decreased S100A9 levels on ASMCs proliferation, which could potentially provide new insight into the regulation of asthma airway remodeling." (PMID 28050155, 2016). "However, S100A9 level was elevated in serum of bakery workers and involved in innate immune responses of baker's asthma pathogenesis." (PMID 28050155, 2016). "Moreover, the inhibition of S100A8 and S100A9 reduced the migration of inflammatory cells into the lungs in a mouse model of asthma." (PMID 23304218, 2012). "Other reports have shown that S100A9 is involved in asthma via initiating and intensifying neutrophilic inflammation, contributing to the disease process, and playing a protective role in asthma-related airway hyper-responsiveness by inhibiting the contraction of airway smooth muscles." (PMID 39064796, 2024).
asthma (continued). "Therefore, S100A9 may initiate and amplify neutrophilic inflammation in patients with uncontrolled, severe asthma and could be used as a biomarker of neutrophilic inflammation in this group of patients." (PMID 33567747, 2021). "Sputum S100A9 levels may represent a biomarker for severe neutrophilic uncontrolled asthma." (PMID 29359169, 2017). "Moreover, the inhibition of S100A8 and S100A9 could reduce the migration of inflammatory cells into the lungs in a mouse model of asthma." (PMID 20691077, 2010). "Their increased activity is found in the sputum of patients with asthma, which translates into the presence of the S100A8/S100A9 complex, which is largely correlated with the severity of the disease." (PMID 40723867, 2025). "S100A8, S100A9, S100A12, and RETN are universally upregulated in various cell types of asthma patients." (PMID 41550933, 2025). "In expression feature analyses, we observe universal upregulation of S100A8, S100A9, S100A12, and RETN in various cell types of asthma patients, particularly S100A8 and S100A9." (PMID 41550933, 2025). "This goes along with the lines of studies reporting higher S100A9 or calprotectin expression in serum with lower FEV1/FVC ratio, increased airway hyper-reactivity, or uncontrolled asthma." (PMID 37996952, 2023). "A study using an asthma murine model challenged with A. fumigatus mixed with OVA showed that neutralizing antibodies against S100A8 and S100A9 alleviated airway inflammation and eosinophil recruitment." (PMID 37996952, 2023). "Employing shotgun proteomics, ten proteins were found significantly up-regulated in asthma, including SERPINA1; meanwhile, seven proteins were significantly downregulated in asthmatics like S100A9, S100A8, SMR3B, and SCGB1A1." (PMID 35628512, 2022). "Asthmatic patients with higher S100A9 levels had lower PC20 methacholine values and a higher prevalence of severe asthma (SA) (P < .050)." (PMID 34285336, 2021). "The S100A9 protein binds to the proinflammatory receptors involving RAGE and TLR4, both of which are involved in the pathogenesis of asthma." (PMID 33791048, 2021). "Additionally, S100A9 directly induces neutrophil degranulation and chemotaxis and leucocyte adhesion and endothelial transmigration which may be the main mechanism for airway neutrophilia in asthma." (PMID 33791048, 2021). "In the lung, increased levels of S100A8, S100A9 and S100A12 have been found in asthma, cystic fibrosis, chronic obstructive pulmonary disease, idiopathic pulmonary fibrosis, acute respiratory distress syndrome and ventilator associated lung injury." (PMID 25706559, 2015). "S100A9 protein binds to the proinflammatory receptors, receptor for advanced glycation end products (RAGE) and Toll-like receptor 4 (TLR4), both of which are involved in the pathogenesis of asthma." (PMID 33791048, 2021). "S100A9 and/or S100A8/A9 may also have an anti-inflammatory function in asthma by downregulating the function of CD4+ Treg cells." (PMID 34239729, 2021). "In contrast, CRAMP, S100A8, and S100A9 were significantly decreased in the lung tissues of allergen HDM-challenged mice, a model of airway inflammation that is used for preclinical studies of asthma." (PMID 32973796, 2020). "Acupuncture could inhibit the S100 protein/RAGE-mediated inflammatory signaling pathway by downregulating the proteins S100A8, S100A9, and RAGE while upregulating sRAGE expression, which would to reverse the inflammatory process of asthma." (PMID 23304218, 2012). "In our studies, the increased expression levels of S100A8, S100A9, and S100A11 in asthma onset in rats were downregulated after acupuncture, which suggests that acupuncture had an effect on the regulation of inflammatory reactions in asthma." (PMID 23304218, 2012). "In summary, decreased S100A9 expression promoted rat ASMCs proliferation by stimulating ROS generation and inhibiting p38 MAPK, which may provide new insights into the regulation of asthma airway remodeling." (PMID 28050155, 2016).
asthma (continued). "Acupuncture can systematically regulate this inflammatory signaling pathway at different levels through the regulation of several key nodal proteins, including CC10, S100A8, S100A9, RAGE, sRAGE, and RhoGDI2, which may explain, at least in part, the anti-inflammatory effect of acupuncture in asthma." (PMID 23304218, 2012).